ANGPTL3 (angiopoietin like 3)
Diseases named in the same sentence as ANGPTL3 in open-access papers (continued):
Sharing a sentence is not in itself a finding about the gene and the disease.
prediabetes (2 papers, 2019 to 2020). "We, therefore, investigated the effect of short-term cooling on plasma ANGPTL3 and ANGPTL8, in comparison with ANGPTL4, in relation to changes in lipid metabolism in young, healthy, lean men as well as middle-aged men with overweight and prediabetes." (PMID 31416197, 2019). "However, in case of ANGPTL3, plasma levels increased in white Caucasian but not South Asian middle-aged men with overweight and prediabetes." (PMID 31416197, 2019). "In middle-aged men with overweight and prediabetes, short-term cooling only significantly increased plasma ANGPTL4 levels (+15%, p < 0.05), but not ANGPTL3 (230 ± 9 vs. 251 ± 13 ng/mL, p = 0.051) or ANGPTL8 (2.2 ± 0.5 vs. 2.3 ± 0.5 μg/mL, p = 0.46)." (PMID 31416197, 2019). "Therefore, we speculate that the absent cold-induced changes in ANGPTL3 and ANGPTL8 in middle-aged men with overweight and prediabetes might reflect an attempt of the body to overcome impaired glucose uptake by insulin-resistant BAT." (PMID 31416197, 2019).
abdominal aortic aneurysm (1 paper, 2021). Enlargement and ballooning of the vessel that supplies arterial blood to the abdomen, pelvis and legs. "We found a weak association between TG-lowering therapies and aortic (ANGPTL3, 0.51, 0.29–0.89) and abdominal aortic aneurysms (LPL, 0.64, 0.44–0.94)." (PMID 34834523, 2021).
Abdominal obesity (1 paper, 2019). Excessive fat around the stomach and abdomen. "In our study, we also confirmed there was a positive correlation between serum ANGPTL3 and BMI (r = 0.367, P = 0.000), and the difference was statistically significant, suggesting that abdominal obesity was associated with ANGPTL3." (PMID 31103046, 2019).
abetalipoproteinemia (1 paper, 2018). "Other primary forms include abetalipoproteinemia, characterized by a virtual absence of apoB-containing lipoproteins, the Anderson disease, or chylomicron retention syndrome, and combined familial hypolipidemia, which is due to a mutation of the gene for the angiopoietin-like 3 (ANGPTL3) protein." (PMID 30558209, 2018).
acute kidney injury (1 paper, 2023). Sudden and sustained deterioration of the kidney function characterized by decreased glomerular filtration rate, increased serum creatinine or oliguria. "Additionally, Angptl3 knockout alleviated the apoptosis of podocytes by regulating the ROS/GRP78 signaling pathway in lipopolysaccharide (LPS)-induced acute kidney injury." (PMID 37266537, 2023).
acute monocytic leukemia (1 paper, 2024). Acute monoblastic leukemia (AML-M5), is one of the most common subtypes of acute myeloid leukemia (AML) that is either comprised of more than 80% of monoblasts (AML-M5a) or 30-80% monoblasts with (pro)monocytic differentiation (AML-M5b). "We next determined the effects of ANGPTL3 on NF-κB activation in immune cells by knocking down ANGPTL3 in THP1 cells, a human monocyte cell line from acute monocytic leukemia, and confirmed that the knockdown of ANGPTL3 in THP1 cells also potentiated IL-1β-induced transcription of downstream genes." (PMID 37634084, 2024).
aortic aneurysm (1 paper, 2021). A ruptured aneurysm located in the wall of the proximal portion of the descending aorta proceeding from the arch of the aorta. "Regarding the genetically proxied TG-lowering inhibition, ANGPTL3 variants were associated with lower risk of aortic aneurysms (OR = 0.51, 95% CI = 0.29–0.89, p = 0.02) and cerebral aneurysms in the UK Biobank cohort (OR = 0.12, 95% CI = 0.02–0.62, p = 0.012)." (PMID 34834523, 2021). "Apart from HMGCR and PCSK9 inhibitions, ANGPTL3 might be another potential target for the treatment of aortic aneurysms in our study." (PMID 34834523, 2021).
B-cell acute lymphoblastic leukemia (1 paper, 2014). A neoplasm of lymphoblasts committed to the B-cell lineage, typically composed of small to medium-sized blast cells. "As overexpression of Angptl3 down-regulates Ikaros in HSCs, and since Ikaros deletions are frequently observed in B-cell acute lymphoblastic leukemias, this may provide an alternative explanation for the reduced circulating mature B-cells following transplantation of Angptl3-overexpressing HSCs." (PMID 25170927, 2014).
bone cancer (1 paper, 2021). A primary or metastatic malignant neoplasm affecting the bone or articular cartilage. "ANGPTL-4 has already been shown to be up-regulated by TGF-β in breast and bone cancer, but the relationship between ANGPTL-3 and TGF-β is not so clear." (PMID 34360721, 2021).
breast disease (1 paper, 2022). "The sample size could also be insufficient to reveal associations between ANGPTL3, or Lipoprotein (a), and the severity of the breast disease." (PMID 36203122, 2022). "In the present study, we investigated the levels of PCSK9, ANGPTL3 and Lp(a) in women with breast diseases of increasing severity (benign, stage 0 and stage III cancers)." (PMID 36203122, 2022). "In contrast, ANGPTL3 and Lp(a) plasma levels did not display any association with breast disease status and lipids did not correlate with disease severity." (PMID 36203122, 2022). "Next, we investigated the relationship between severity of breast disease and the lipid profile, PCSK9, ANGPTL3 and Lp(a) plasma levels, adjusted for age and BMI." (PMID 36203122, 2022). "In our study, no statistical differences in ANGPTL3 or Lp(a) levels were observed between groups of increasing breast disease severity." (PMID 36203122, 2022).
Cirrhosis (1 paper, 2021). A chronic disorder of the liver in which liver tissue becomes scarred and is partially replaced by regenerative nodules and fibrotic tissue resulting in loss of liver function. "Post hoc analysis revealed significant differences in the ANGPTL-3 serum levels between the pairs acute infection–advanced fibrosis (p-value = 0.027), mild fibrosis–advanced fibrosis (p-value = 0.000) and cirrhosis–advanced fibrosis (p-value = 0.001)." (PMID 34360721, 2021). "ANGPTL-3 was decreased in patients with advanced fibrosis compared to other disease stages, while ANGPTL-4 was progressively increased from acute infection to cirrhosis and HCC, peaking at the advanced fibrosis stage." (PMID 34360721, 2021). "Surprisingly, this did not happen to ANGPTL-3 when treatment was administered to patients with advanced fibrosis and cirrhosis." (PMID 34360721, 2021). "However, in opposition to ANGPTL-3, ANGPTL-4 levels peaked in the advanced fibrosis group, with a value of 102.8 ng/mL, and remained relatively high in the cirrhosis and HCC groups." (PMID 34360721, 2021). "DAA treatment did not alter ANGPTL-3 levels in advanced fibrosis/cirrhosis and in HCV infection in vitro, in contrast to ANGPTL-4." (PMID 34360721, 2021). "Therefore, we determined the levels of the active TGF-β peptide in patients with mild/advanced fibrosis and cirrhosis in an effort to see whether TGF-β is the link between fibrosis and the expression patterns of ANGPTL-3 and ANGPTL-4." (PMID 34360721, 2021). "Interestingly, both ANGPTL-3 and ANGPTL-4 serum levels did not statistically differ between the early stages of acute infection and mild fibrosis or the late stages cirrhosis and HCC." (PMID 34360721, 2021).
dengue fever (1 paper, 2014). "Our findings suggest that Angptl3 may participate in pathologic processes in dengue virus infection, with a possible role in modulating endothelial permeability, a hallmark of severe dengue." (PMID 24444080, 2014). "Nine biomarkers differed significantly between dengue fever and leptospirosis, with higher levels of Angptl3, IL-18BP, IP-10/CXCL10, Platelet Factor 4, sICAM-1, Factor D, sEng and sKDR in dengue and higher levels of sTie-2 in leptospirosis (p < 0.001 for all comparisons)." (PMID 24444080, 2014). "Median levels of Angptl3, IL-18BP, CXCL10, Platelet Factor 4, sICAM-1, Factor D, sEng and sKDR were higher in dengue fever compared to leptospirosis (p < 0.001 for all)." (PMID 24444080, 2014). "There were five biomarkers where the median levels were outside the population-derived normal range in dengue fever, but not leptospirosis: Angptl3, IL-18BP, CXCL10, sICAM-1, and sEng." (PMID 24444080, 2014). "Circulating levels of Angptl3 and Angptl4 have not previously been studied in dengue or leptospirosis." (PMID 24444080, 2014).
depression (1 paper, 2019). "For example, proteomic research suggests that the serum levels of c-reaction protein (CRP), inter-alpha-trypsin inhibitor heavy chain H4 (ITIH4), serum amyloid A1 (SAA1), and angiopoietin-like 3 (ANGPTL3) are significantly higher in patients with depression than in healthy controls." (PMID 31719821, 2019).
diabetic retinopathy (1 paper, 2023). "This is the first report on serum levels of ANGPTL3 in patients with DN, while there are studies that reported ANGPTL3 in diabetic retinopathy and primary nephrotic syndrome." (PMID 37312105, 2023).
fibrosis (1 paper, 2021). the formation of excess fibrous connective tissue in an organ or tissue in a reparative or reactive process. "Then, ANGPTL-3 levels kept decreasing and reached their minimum in the advanced fibrosis group (332.1 ng/mL), after which they started increasing again." (PMID 34360721, 2021). "We used ELISA and RT-qPCR to investigate ANGPTL-3 and ANGPTL-4 expression in HCV patients with characterised fibrosis throughout the natural history of hepatitis C and in long-term HCV infection in vitro, before and after DAA treatment." (PMID 34360721, 2021).
graft versus host disease (1 paper, 2022). An immune system disorder that occurs after allogeneic hematopoietic stem cell transplant and is a reaction of donor immune cells against host tissues. "Our result presented the same trend as ANGPTL3 and ApoH genes were both reduced in IF/TA group, and we observed that those genes were both related to allograft rejection and graft-versus-host disease." (PMID 35755170, 2022).
head and neck squamous cell carcinoma (1 paper, 2023). A squamous cell carcinoma that arises from any of the following anatomic sites: lip and oral cavity, nasal cavity, paranasal sinuses, pharynx, larynx, and salivary glands. "The expression of ANGPTL3 is significantly upregulated in head and neck squamous cell carcinoma (HNSCC), where it triggers the ERK pathway and promotes cell proliferation." (PMID 37375208, 2023).
hepatitis C (1 paper, 2021). "In conclusion, we investigated, for the first time, ANGPTL-3 and ANGPTL-4 expression throughout the natural history of hepatitis C in vivo and long-term HCV infection in vitro and then determined the corresponding ANGPTL levels after treatment with DAAs." (PMID 34360721, 2021). "Firstly, we characterised the expression patterns of the host lipid regulatory factors ANGPTL-3 and ANGPTL-4 throughout the natural course of hepatitis C in vivo and HCV infection in vitro." (PMID 34360721, 2021). "The present study mainly determined the serum levels of the host lipid regulators ANGPTL-3 and ANGPTL-4 in HCV patients throughout the natural history of hepatitis C, from acute infection to HCC." (PMID 34360721, 2021).
hepatocellular adenoma (1 paper, 2023). A benign epithelial neoplasm arising from the hepatocytes. "It has been shown that ANGPTL-3 modulation by the viral core protein through a process that may be linked to deregulated glycolysis, enhanced hepatic lipogenesis, and a steatotic phenotype in hepatocellular adenomas may contribute to persistent HCV manifestations and the development of HCC." (PMID 36830808, 2023).
hyperthyroidism (1 paper, 2024). Overactivity of the thyroid gland resulting in overproduction of thyroid hormone and increased metabolic rate. "In contrast, LPL activation, known as the primary action of ANGPTL3 inhibitors, was found to be related to an increased risk of hyperthyroidism." (PMID 38425755, 2024).
liver inflammation (1 paper, 2018). "Together with our results regarding CK-18, it could indicate that an increase in plasma ANGPTL3 concentration is the result of liver inflammation or that ANGPTL3 plays a role in the development of the diseased condition." (PMID 29619113, 2018).
lung adenocarcinoma (1 paper, 2022). A carcinoma that arises from the lung and is characterized by the presence of malignant glandular epithelial cells. "Linc00665 directly interacts with the YB-1 protein to promote its stabilization, leading to the nuclear accumulation of YB-1, acting as a transcription factor to activate the expression of angiopoietin-like protein 3/4 (ANGPTL3/4) to promote angiogenesis in lung adenocarcinoma." (PMID 35406781, 2022).
malaria (1 paper, 2019). Malaria is a serious and sometimes fatal disease caused by a parasite that commonly infects a certain type of mosquito which feeds on humans. "Altered kinetics were also observed in women with malaria at Visit 1 for the following angiogenic and metabolic factors: sEng (χ2 = 38.3, p < 0.001), Angptl3 (χ2 = 13.3, p = 0.001), and Leptin (χ2 = 13.2, p = 0.001)." (PMID 31574087, 2019).
malnutrition (1 paper, 2018). Inadequate nutrition resulting from poor diet, malabsorption, or abnormal nutrient distribution. "SBS as a model of extreme malnutrition was associated with substantially elevated levels of both ANGPTL3 and 4, which might at least partially be attributed to their initially increased proinflammatory status as evidenced by markedly high CRP levels." (PMID 29695708, 2018).
metastasis (1 paper, 2023). The spread or migration of cancer cells from one part of the body (where they first appeared) to another. "Previous research has shown a correlation between ANGPTL3 and liver metastasis in CRC." (PMID 38127052, 2023).
myocardial ischemia (1 paper, 2018). A disorder of cardiac function caused by insufficient blood flow to the muscle tissue of the heart. "Therefore, we hypothesized that ANGPTL3 could improve function of EPCs by binding to integrin ανβ3 receptors and up-regulating miR-126 expression via activating AKT, thus promoting the formation of new blood vessels, attenuating myocardial ischemia and improving heart function." (PMID 30086775, 2018).
neuroendocrine lung neoplasms (1 paper, 2025). "Angiopoietin-like protein 3 (ANGPTL3), a liver-derived protein involved in lipid metabolism and angiogenesis, has shown differential expression in LNETs compared to other high-grade neuroendocrine lung neoplasms such as LCNEC and SCLC." (PMID 40869558, 2025).
non-proliferative diabetic retinopathy (1 paper, 2025). Early stage diabetic retinopathy, characterized by the absence of neovascularisation of the retina. "Furthermore, in comparison to non-proliferative diabetic retinopathy (NPDR) patients, elevated serum ANGPTL3 levels in T2DM patients were associated with a heightened risk of PDR, suggesting that ANGPTL3 may play a crucial role in the progression of DR." (PMID 40559376, 2025).
osteonecrosis (1 paper, 2025). A none disease characterized by death of bone tissue due to a lack of blood supply. "Conversely, we found that genetic mimicry of ANGPTL3 inhibition increases the risk of osteonecrosis." (PMID 41294017, 2025). "HMGCR expression in blood tissue and osteonecrosis shared a causal variant (rs6453133) (blood tissue: PP.H4 = 0.999), whereas the colocalisation finding of ANGPTL3 expression was poorly identified (liver tissue: PP.H4 = 0.012)." (PMID 41294017, 2025). "Furthermore, ANGPTL3 expression was linked to a lower risk of osteonecrosis (IVW: OR = 0.76 [95% CI, 0.58–0.99]; p = 0.04)." (PMID 41294017, 2025). "An interesting finding was noted for the genetic mimicry of ANGPTL3 inhibition on the harmful effect of osteonecrosis risk in the MR analysis (OR = 2.99 [95% CI 1.39–6.44], p = 5.2 × 10−3) and this observation was validated in GRS analysis (OR = 1.004 [95% CI 1.001–1.007], p = 0.004)." (PMID 41294017, 2025). "Further investigation into more stringent LD thresholds did not significantly affect the width of confidence intervals or the stability of MR results for both HMGCR and ANGPTL3 in relation to osteonecrosis." (PMID 41294017, 2025). "This may be because ANGPTL3 itself has a vital role in promoting angiogenesis, and inhibiting ANGPTL3 may lead to impaired angiogenesis and worsening of osteonecrosis, which needs to be further studied." (PMID 41294017, 2025).
preeclampsia (1 paper, 2021). Preeclampsia is a hypertensive disorder of pregnancy that is characterized by new-onset hypertension with proteinuria presenting after 20 weeks of gestation, and depending on mild or severe forms may initially present with severe headache, visual disturbances, and hyperreflexia. "Since nothing is known about ANGPTL3 role in normal pregnancy and preeclampsia, we hypothesized that the pregnancy-induced increased in TG levels could be, at least in part, mediated by ANGPTL3." (PMID 33927698, 2021). "The serum levels of ANGPTL3 in women who developed preeclampsia are not statistically different from those observed in healthy pregnant women in each trimester of pregnancy." (PMID 33927698, 2021). "In addition, serum levels of ANGPTL3 in women who developed preeclampsia are not statistically different from the levels observed in healthy pregnant women throughout the three trimesters of pregnancy studied." (PMID 33927698, 2021).
prostate carcinoma (1 paper, 2025). A carcinoma that arises from epithelial cells of the prostate gland. "Measured prostate‐specific antigen (PSA) levels are correlated with the lipid profile and ANGPTL3 levels in men at risk for prostate cancer but no longer display this correlation in men diagnosed with prostate cancer." (PMID 39888285, 2025). "Tumor‐induced variations of ANGPTL3 and uptake of HDL‐cholesterol by cancer cells have been reported, perhaps explaining the disruption between ANGPTL3 levels and HDL in ovarian and prostate cancers." (PMID 39888285, 2025).
renal fibrosis (1 paper, 2022). A final common manifestation of a wide variety of chronic kidney diseases characterized by glomerulosclerosis and tubulointerstitial fibrosis. "In summary, our findings suggest that anti-ANGPTL3/IL22 fusion protein protects the kidney by reducing proteinuria and renal fibrosis as well as stabilizing the endocrine environment in the treatment of DN." (PMID 36544775, 2022). "Our results indicated that anti-ANGPTL3/IL22 administration attenuated podocyte injury and ACR, while ameliorating renal fibrosis and regulating glucolipid metabolism by suppressing the inflammatory response." (PMID 36544775, 2022). "Taken together, anti-ANGPTL3/IL22 significantly moderated kidney collagen accumulation and suppressed the expression of fibrosis-related proteins in DN, which might ultimately alleviate renal fibrosis." (PMID 36544775, 2022).
Sepsis (1 paper, 2025). Sepsis is defined as life-threatening organ dysfunction caused by a dysregulated host response to infection. "SNPs that reduce the activity of ANGPTL3 had an obvious protective effect on sepsis in both the IVW method (OR 0.676, 95% CI 0.525–0.870; P = 0.002) and weighted median method (OR 0.664, 95% CI 0.501–0.881; P = 0.004)." (PMID 40934270, 2025). "Additionally, only TG-lowering genetic variants in ANGPTL3 and LPL were associated with lower sepsis risk in our study." (PMID 40934270, 2025). "Moreover, genetic mimicry near the ANGPTL3 and LPL gene suggested that reducing the activity of ANGPTL3 and LPL (mimicking antisense anti-ANGPTL3 and LPL agents) was forecasted to decrease sepsis risk." (PMID 40934270, 2025). "Notably, we have identified ANGPTL3 and LPL as potential drug targets that significantly lowered the risk of sepsis." (PMID 40934270, 2025). "Within the 9 lipid-lowering drug targets investigated ANGPTL3 and LPL exhibit potential as candidate drug targets for sepsis." (PMID 40934270, 2025). "Our study provided strong evidence that ANGPTL3 and LPL are promising drug targets for sepsis." (PMID 40934270, 2025). "Moreover, this study demonstrates that ANGPTL3 and LPL are promising candidate drug targets for the treatment of sepsis." (PMID 40934270, 2025).